IL1B (interleukin 1 beta)
Diseases named in the same sentence as IL1B in open-access papers (continued):
Sharing a sentence is not in itself a finding about the gene and the disease.
COVID-19 (continued). "A leading, indirect pathway is inflammation-driven tumor promotion, particularly through IL-6/JAK–STAT3, IL-1β/NLRP3, TNF-α/NF-κB, and ELR+ CXC chemokines (e.g., IL-8/CXCL8), which are all engaged during COVID-19 and have established roles in lung tumor biology." (PMID 41440526, 2025). "Considering the great importance of TNF, IL-1β, and IL18 in the pathogenesis of COVID-19, and in order to evaluate whether their levels were lower in mild cases than in severe cases, we analyzed their average expression levels in all groups of patients." (PMID 40141410, 2025). "Pro-inflammatory cytokines, such as IL-6, IL-1β, and TNF-α, are known to induce F3 gene expression in both immune and non-immune cells, potentially contributing to the thromboembolic events observed in COVID-19 patients, particularly in severe cases." (PMID 41583455, 2025). "The elevated IL-1β finding here in all COVID-19-infected individuals, regardless of lingering sequelae, is consistent with other published reports." (PMID 38534322, 2024). "Importantly, elucidation of putative serum mediators revealed a significant upregulation of key cytokines in COVID-19 positive patients compared to controls, including IL-6, TNF-α, IL-1β, IL-10, and CRP." (PMID 38041432, 2024). "Furthermore, COVID-19 mRNA-LNP vaccines encompass adjuvants, such as LNPs, which trigger inflammatory cytokines, including interleukin (IL)-1β and IL-6." (PMID 39452475, 2024). "Furthermore, elevated pro-inflammatory cytokines such as IL-6, IL-1β, and monocyte chemoattractant protein 1 (MCP-1) in COVID-19 patients affect endothelial function and integrity." (PMID 38214889, 2024). "For this purpose we relied on the Comparative Toxicogenomic Database (CTD), GeneMANIA, and ToppGene Suite portal and identified a set of five common genes (IL1B, CXCL8, IL6, IL10, TNF) for the six metals and COVID-19, all of which code for pro-inflammatory and anti-inflammatory cytokines." (PMID 38963144, 2024). "Interestingly, the only cytokine whose levels significantly differed between COVID-19-infected patients and SARS-CoV-2/DENV-infected patients was interleukin 1β (IL-1β)." (PMID 39583156, 2024). "The primary objective of this study is to assess the predictive value and diagnostic potential of specific interleukins (IL-10, IL-17A, IL-1β, IL-6), chemokines (CXCL), and monocyte chemoattractant protein (MCP) in predicting severe COVID-19 outcomes and mortality." (PMID 39062105, 2024). "The group with severe/critical COVID-19 had more abnormalities in many laboratory indicators, including lower levels of autophagy markers (BECN1 and ATG7) and vitamin D, and higher levels of inflammatory markers (TNF-α and IL-1β)." (PMID 38783947, 2024). "Glutamine supplementation (10 g/3x daily) for 5 days could reduce serum levels of IL-1β, hs-CRP, TNFα and increase appetite in COVID-19 patients with pulmonary complications." (PMID 38555403, 2024). "Additionally, the distribution of the haplotypes of NLRP3, NLRC4, NLRP1, CARD8, CASP1, IL1B, and ATG16L1, with a frequency greater than 5% in HC, were similar between COVID-19 patients with mild, moderate, severe, and critical infection, and HC." (PMID 38612539, 2024). "Lastly, interleukins IL-1β, IL-6, and tumor necrosis factor plasma levels are elevated in PASC sufferers, and are also correlated to cognitive impairment in Alzheimer's disease, and with severity of hyposmia after COVID-19." (PMID 39839305, 2024). "The role of serological components in causing cardiovascular damage in COVID-19 is further corroborated by a significant negative correlation of IL-6, TNF-α, IL-1β, IL-10, and CRP levels with cardiomyocyte viability." (PMID 38041432, 2024). "Melatonin could resolve hyper-inflammatory conditions in COVID-19 and PASC by down-regulating proinflammatory cytokines (i.e., TNF-α, IL-1β, IL-6, and IL-8) and increasing anti-inflammatory cytokines such as IL-10660,661." (PMID 38555403, 2024).
COVID-19 (continued). "It has been shown that proinflammatory cytokines and chemokines, including IL-1β, TNF-α, IL-6, interferon gamma-induced protein-10, monocyte chemoattractant protein-1, and macrophage inflammatory proteins 1-α, were significantly elevated in COVID-19 patients." (PMID 39195168, 2024). "Indeed, significant correlations exist between levels of TNF-α, IL-6, IL-1β, IL-10, IFN-γ, and CCL2 with cognitive and behavioral changes in COVID-19 patients, thus showing generalized neuroinflammation." (PMID 39767737, 2024). "In this first study of its kind designed to assess the impact of RIC on inflammatory cytokines in participants admitted to hospital with COVID-19, we were unable to detect a significant reduction by RIC in levels of pro-inflammatory cytokines (including IL-1β, IL-6, and TNF-α)." (PMID 36445625, 2024). "In additional experiments, we also investigated the potential action of the nutraceutical formula on other inflammatory genes with a role in innate immunity (i.e., C3, IL-1β, IL-6, CXCL10 and CXCL12) whose modulation have been reported in COVID-19 pathogenesis and progression." (PMID 38886736, 2024). "Acute respiratory SARS-CoV-2 infection generates a robust systemic cytokine response in addition to type I and type II interferon responses, and the plasma levels of IFN-α, IFN-γ, IL-1β, IL-6, and TNF-α are significantly increased in human patients with acute COVID-19." (PMID 39062017, 2024). "U tu su svrhu korišteni Komparativna toksikogenomska baza podataka (CTD), GeneMANIA i ToppGene Suite portal te je identificirana skupina od pet zajedničkih gena (IL1B, CXCL8, IL6, IL10, TNF) za šest metala i COVID-19, koji svi kodiraju proinflamatorne i antiinflamatorne citokine." (PMID 38963144, 2024). "Among patients enrolled within 7 days of symptom onset, evidence of pro-inflammatory monocyte/macrophage (IL-1Ra, IL-1β, IL-6, CXCL10), NK cell (IL-15), Th1/Th17-pathway (IL-7, IL-15, IL-17F), and endothelial (VEGF-A) activation were apparent in patients with severe COVID-19." (PMID 38368384, 2024). "Severe adult COVID-19 and MIS-C are characterized by excessive inflammation, including elevated inflammatory cytokines and chemokines such as tumor necrosis factor alpha (TNF-α), interleukin (IL) 6, IL-10, and IL-1β." (PMID 39494457, 2024). "COVID-19 exhibited a distinct immunological profile characterized by increased levels of Th1 (IL-12 and IFN-γ) and Th2 (IL-4, IL-5, IL-10, and IL-13) cytokines, along with IL-1β and IL-6, among other markers." (PMID 39408907, 2024). "Also, increased levels of the endothelial tPA receptor, annexin A2, correlated with inflammatory markers (i.e., IL-1β, IL-6, and TNF-α) and COVID-19 magnitude." (PMID 38378550, 2024). "Although the prognostic value of TNF-α and IL-1β as therapeutic targets in COVID-19 is not known, they are important makers of disease severity in other infectious and inflammatory conditions." (PMID 36445625, 2024). "S protein selectively promoted inflammasome formation and IL-1β secretion in macrophages isolated from COVID-19 patients but not in non-COVID-19 subject-derived macrophages." (PMID 37251383, 2023). "Additionally, IL1B and IFITM3 were found to be upregulated in these cells in patients with severe COVID-19, when compared to healthy or asymptomatic individuals or patients with mild disease." (PMID 37795240, 2023). "IL-1β and TNF are involved in the process of increased vascular permeability, vascular leakage, and coagulation, which results in vascular leakage, pulmonary edema, and disseminated intravascular coagulation in severe COVID-19 patients." (PMID 36769328, 2023). "The original level of IL-1β showed no statistical significance (p = 0.9701) with COVID-19 mortality." (PMID 37735372, 2023). "However, HD patients with COVID-19 symptom worsening showed up-regulation (more than 2.5-fold increase) of GM-CSF, IFN-γ, IL-1β, IL-2, IL-6, IL-17A and IL-21, and down-regulation of TNF-α and IL-8 serum levels after the dialysis procedure." (PMID 36675231, 2023).
COVID-19 (continued). "This study also showed that the serum level of IL-1β was not significantly increased in patients with COVID-19 than in the HS group." (PMID 37723427, 2023). "Our study includes both symptomatic COVID-19 positive PCR and symptomatic negative PCR patients for COVID-19 and compare the tested cytokines (IL-1β and IL-8), and miRNA (miRNA-618 and miRNA-16–2-3p) in both groups." (PMID 37222789, 2023). "COVID-19 is characterized by increased interferon-γ (IFN-γ) and IL-1β, IL-4, and IL-10 production." (PMID 38131979, 2023). "Acute COVID-19 children had significantly elevated levels of cytokines, (Interferon (IFN)) IFNγ, Interleukins (IL)-2, TNFα, IL-1α, IL-1β, IFNα, IFNβ, IL-6, IL-12, IL-17A and Granulocyte-Colony Stimulating Factors (G-CSF) in comparison to convalescent COVID-19 and controls." (PMID 37013538, 2023). "On the contrary, canakinumab, another IL-1-β inhibitor drug that is under investigation for the possibility of its use in the treatment of COVID-19, is not effective in the treatment of newly diagnosed DM-I." (PMID 37187644, 2023). "We reported that COVID-19 patients have significantly higher IL-1β and IL-6 plasma levels compared to non-COVID-19 pneumonia patients." (PMID 37986089, 2023). "Clinical data indicate that a hyperinflammatory response (an excessive release of pro-inflammatory cytokines e.g. interleukin 6 (IL-6) and IL-1b with secondary tissue damage) to SARS-CoV-2, contributes to disease severity and death in patients affected by COVID-19." (PMID 38034686, 2023). "The VAPrapid2 trial conducted among non-COVID-19 patients at VAP suspicion found no impact on antibiotic consumption of therapy guided by BAL IL-1β and IL-8 measurement compared to routine management." (PMID 37749631, 2023). "The absence of significant differences in serum IL-1β levels challenges the notion that IL-1β is the sole driver of inflammation in COVID-19." (PMID 37723427, 2023). "Monocytes of HD + COVID-19 patients secreted significant higher levels of the pro-inflammatory cytokines GM-CSF, IL-1β, IL8, IL-10, CCL2 and CCL3 compared to non-infected HD patients." (PMID 36675231, 2023). "High expression levels of IL-1β and IFN-γ have been detected in patients with COVID-19." (PMID 37112918, 2023). "However, some cytokines, including IL-1β, IL-3, IL-17, and CCL3, were uniquely activated in severe COVID-19." (PMID 37373331, 2023). "IL-1β and other cytokines related to CRS showed a positive correlation in severe COVID-19 patients." (PMID 36769328, 2023). "However, SARS-CoV-2 infection has been shown to suppress type I IFN antiviral responses (e.g., IFN-α and IFN-β) and elevate the production of inflammatory cytokines (e.g., IL-1β, IL-6, and TNF-α) in blood and lung samples from COVID-19 patients." (PMID 36883057, 2023). "BAL alveolar macrophages from severe COVID-19 patients (n = 23) were characterized by an increased production and release of several pro-inflammatory mediators, such as IL-1β, IL-6, CCL3 and CCL4 and increased expression of IL-1R and S100A8/9 proteins, compared to those from mild COVID-19 patients." (PMID 36941580, 2023). "A previous study showed that the plasma cytokine levels such as IL-6, IL-1β, IL-10, IL-21, and TNF-α were significantly higher in asymptomatic group compared to the controls, indicating an increased inflammation in asymptomatic COVID-19 patients." (PMID 37869674, 2023). "IL-6, IL-1β, and TNF-α are all key cytokines in both COVID-19 and RA." (PMID 37163438, 2023). "Given the growing body of evidence linking dysregulated immune responses and cytokine storm to severe COVID-19 outcomes, investigating the gene expression of NLRP1, NLRP3, and ASC, as well as the serum levels of IL-1β, in patients with COVID-19 is of paramount importance." (PMID 37723427, 2023). "The long-COVID-19 group has presented significantly high levels of IL-1β and IL-6 compared to unexposed individuals, but not from recovered COVID-19." (PMID 37018291, 2023).
COVID-19 (continued). "Recently, COVID-19 patients were shown to have higher levels of Gal-3, TNF-α, IL-1β, and IL-6." (PMID 37112643, 2023). "Plasma levels of IL-1β (presumably among others) have been shown to be elevated, at least temporarily, not only during the acute phase of SARS-CoV-2 infection but even in individuals who have recovered from COVID-19." (PMID 37239926, 2023). "Notably, circulatory exosomes from severe COVID-19 patients were able to increase the expression of NLRP3, caspase-1 and IL-1β in endothelial cells." (PMID 37251383, 2023). "A similar time-dependent increase has been reported for IL-6, IL-8, IL-1β, and TNF-α in COVID-19." (PMID 38069209, 2023). "In serum collected 1–11 days after onset of SARS-CoV-2 infection, median IL-1β in 4 asymptomatic persons infected with SARS-CoV-2 was 6.67 pg./mL, 13.07 pg./mL was measured in 66 symptomatic persons with COVID-19, and in 4 healthy controls median IL-1β was 4.78 pg./mL." (PMID 37928695, 2023). "No significant IL-1β difference between intensive care and non-intensive care COVID-19 patients was observed." (PMID 37928695, 2023). "However, early markedly downregulated FcεR1 gene expression observed in Moderate/Severe COVID-19 suggests an inappropriate response, which is further supported by the down regulated targets such as TNF, PTGS2 and IL-1B." (PMID 37261339, 2023). "After all, the role of IL-1β in COVID-19 is not defined and not always correlated with disease severity." (PMID 37215142, 2023). "First, we confirm previously reported data showing that COVID-19 patients show increased plasma levels of IL-1β and IL-6 compared to pneumonia patients non-SARS-CoV-2 related." (PMID 37986089, 2023). "During the COVID-19 phase, IL1β and IL6 increased by day 90 in Group I, while there was no significant change in Group II." (PMID 37546047, 2023). "Moreover, PD1 is able to decrease the production of IL-1β, a cytokine which plays a pivotal role both in AOSD and COVID-19, from macrophages derived from a mouse model." (PMID 37153620, 2023). "Nevertheless, overall data supported the hypothesis that high IL-1β, IL-6, and TNF-α in the same patient play a role in COVID-19 and periodontitis pathogenicity independently." (PMID 37106750, 2023). "Mean plasma levels of IL-1β and IL-18, as products of inflammasome activity and pyroptosis, were higher in COVID-19 than in the other groups, as was the case for the alveolar cell damage marker sRAGE and GDF15 in the COVID-19 group." (PMID 37582864, 2023). "Interestingly, postmortem lung tissues from patients with lethal COVID-19 as well as PBMCs from severe COVID-19 cases, show a type I IFN response transcriptional signature, along with TNF/IL-1β induction." (PMID 37791071, 2023). "The mediators CCL3, CCL4, CCL2, CCL5, IL-12, IL-15, IL-1Ra, and PDGF were higher in healthy volunteers, while the mediators CCL11, CXCL10, IL-1b, IL-6, TNF-a, IFN-g, IL-17, IL-9, IL-10, IL-13, FGF-basic, G-CSF, GM-CSF, IL-7, and IL-2 were increased in COVID-19 positive patients." (PMID 37903875, 2023). "Of note, nutritional glutamine supplementation caused a decrease of IL-1β, TNF-α and high-sensitivity C-reactive protein (hs-CRP), in COVID-19 patient sera, compared to the non-supplemented control group." (PMID 36984782, 2023). "Interestingly, mounting evidence from clinical studies suggests that this PPAR agonist prevents the ARDS/ALI in COVID-19 patients by downregulating NF-κB and JAK/STAT signaling and then reducing TNF-α, IL1β, and IL6 levels." (PMID 36875108, 2023). "However, most of the included studies indicated elevated serum pro-inflammatory cytokine (IL-1β, IL-6 and TNF-α) levels in diseases (COVID-19/periodontitis) compared to healthy controls included in the same study." (PMID 37106750, 2023). "Additionally, the PCA coordinates obtained from the 3rd trimester demonstrated that several soluble mediators were vectors related to convalescent COVID-19 in pregnant women, except for CXCL10, IL-1β, TNF-α, IFN-γ, PDGF and GM-CSF." (PMID 37122732, 2023).
COVID-19 (continued). "In this study, the relative expression of IRF9, CCL5, IFI6, TGFB1, IL1B, OAS1, and TFRC genes (related to immunity and antiviral activity) was analyzed in upper airway samples from 127 individuals (97 COVID-19 positive and 30 controls) by using a two-step RT-PCR." (PMID 37389217, 2023). "However, significantly higher levels of IL-1β, TNF and IFNγ were found in semen from patients recovered from mild and/or severe COVID-19 with respect to control individuals (p < 0.05, p < 0.05 and p < 0.001, respectively)." (PMID 37497433, 2023). "Hamster models infected with SARS-CoV-2 and patients who died from COVID-19 showed impaired BBB permeability, microglial activation, and increased brain expression of IL-1β and IL6 within the hippocampus and the inferior olivary nucleus of the medulla when compared to the control groups." (PMID 37686360, 2023). "In support of this hypothesis, a recent study found that COVID-19 patients had reduced upregulation of CD80 on monocytes and abrogated release of IL-6, TNF, IL-1a and IL-1b in response to Candida albicans." (PMID 38169876, 2023). "Furthermore, the expression levels of NLRP3, NLRP6, IL-1β, and MARCH7 were decreased in COVID-19 patients, while they rose again in convalescent patients." (PMID 38004809, 2023). "Lung samples from COVID-19 autopsies revealed that the inflamed pulmonary endothelium expressed IL-1β, IL-6, IL-15 and TNF-α, in contrast to non-infected tissue samples, recruiting inflammocytes along the alveolar epithelium." (PMID 37568402, 2023). "Cytokine detection: Comparing cytokine levels quantification in laboratory controls and patients in the 4/6-day collection after study admission, it was seen that non-severe COVID-19 cases showed an increase in IL1β, IL-6, IL-10 and TNF." (PMID 37515295, 2023). "Apart from periodontitis and COVID-19, local (salivary) and systemic (serum) TNF-α/IL-6/IL-1β levels also increased in other inflammatory conditions, such as chronic oral erosive lesions and ulcers, and these cytokine levels were inversely proportional to the IL-10 that regulated epithelial healing." (PMID 37106750, 2023). "Moreover, Proinflammatory cytokines like interleukin (IL)-1β, IL-17, IL-6, also tumour necrosis factor-α (TNF-α) that are involved in AD development are significantly elevated in cerebrospinal fluid of COVID-19 patients." (PMID 38259635, 2023). "Patients diagnosed with COVID-19 had an extreme amount of mRNA generation and production of the cytokines IL-1β, IL-6, TNF-α, and IL-18; however, patients treated with nano curcumin exhibited a substantial decline in IL-6 and IL-1β levels." (PMID 37033493, 2023). "The downregulation of the NF-κB/MAPK signaling pathway was postulated to decrease pro-inflammatory cytokines such as IL-6, TNF-α, IL-1β, CXCL10/IP-10, CCL2/MCP-1, and IL-8, suggesting that it may prevent cytokine storm in COVID-19." (PMID 37298539, 2023). "As reported by others, CRP, IL6, IL1β, but not TGFβ levels increased in patients with more severe stages of COVID-19." (PMID 38313435, 2023). "Severe COVID-19 and advanced age are both correlated with biomarkers of systemic inflammation, such as the neutrophil/leukocyte ratio (NLR), weaker type-I IFN responses, NLRP3 inflammasome activation, and IL-6, IL-12 and IL-1β secretion." (PMID 36680215, 2023). "Indeed, IL-6, IL-1β, and tumor necrosis factor alpha (TNF-α) were found to be significantly elevated in COVID-19 patients." (PMID 37762435, 2023). "Previous studies have shown that, compared with healthy donors, the IL-1β levels in serum from COVID-19 patients were not elevated." (PMID 38004809, 2023). "In fact, previous reports have shown that increased IL-1β levels in PBMCs, serum, or plasma did not correlate with COVID-19 severity." (PMID 37799713, 2023). "Non-severe COVID-19 cases showed an increase in IL1β, IL-6, IL-10 and TNF and severely ill patients had higher levels of the cytokines IL-6, IL-10 and CXCL8." (PMID 37515295, 2023).